CD55 (CD55 molecule (Cromer blood group))
Diseases named in the same sentence as CD55 in open-access papers (continued):
Sharing a sentence is not in itself a finding about the gene and the disease.
Peritoneal Fibrosis (1 paper, 2022). Disorder characterized by a wide range of structural changes in PERITONEUM, resulting from fibrogenic or inflammatory processes. "We demonstrate that the gene expression of the complement molecules (C2, C3, C5, C6) and the inhibitory molecules (CD55) is increased in the abdominal wall of the CHX-induced mouse model of peritoneal fibrosis." (PMID 36359246, 2022).
pneumococcal pneumonia (1 paper, 2011). A febrile disease caused by STREPTOCOCCUS PNEUMONIAE. "To test whether increased granulocyte number exaggerate the innate response in CD55-deficient mice, we applied an acute model of pneumococcal pneumonia." (PMID 21984892, 2011). "To obtain insight in how Cd55-/- mice were protected against lethality during pneumococcal pneumonia, we examined bacterial loads in the lungs and blood 24 h and 48 h after infection." (PMID 21984892, 2011).
polycystic ovary syndrome (1 paper, 2024). A disorder that manifests as multiple cysts on the ovaries. "More importantly, CD55+ hiGC transplantation alleviated polycystic ovary syndrome (PCOS) in a mouse model." (PMID 38192172, 2024).
renal clear cell carcinoma (1 paper, 2021). "The authors found that expression of CD55 and CD59 is increased in renal clear cell carcinoma, which may contribute to the progression of these tumors." (PMID 34572075, 2021). "The histological findings of C3d and C5b-9 on renal tumor cells led to the hypothesis that the complement system could be involved in the immune response against ccRCC expression level and cellular distribution of CD46, CD55, and CD59 on renal clear cell carcinoma cells." (PMID 34572075, 2021).
rheumatic disease (1 paper, 2020). "CD55 and/or CD59 erythrocytes are present in a majority of patients with rheumatic disease." (PMID 33362763, 2020).
sickle cell disease (1 paper, 2020). Sickle cell anemias are chronic hemolytic diseases that may induce three types of acute accidents: severe anemia, severe bacterial infections, and ischemic vasoocclusive accidents (VOA) caused by sickle-shaped red blood cells obstructing small blood vessels and capillaries. "Although these patients expressed decreased CD55 and CD59 expression on RBCs, this could not be linked to disease severity, suggesting that these regulators do not play a significant role in the pathophysiology of hemolysis in sickle cell disease." (PMID 33362763, 2020).
signet ring cell carcinoma (1 paper, 2020). A usually aggressive, poorly differentiated invasive adenocarcinoma characterized by the presence of malignant glandular cells in which the nucleus is pressed to one side by the presence of intracytoplasmic mucus. "SC-1 is an isolated monoclonal IgM from a signet-ring cell carcinoma patient and binds to a carbohydrate modified version of decay acceleration factor B (DAF/CD55), which is highly expressed on tumor cells and aids in immune evasion." (PMID 33013904, 2020).
Splenomegaly (1 paper, 2022). Abnormal increased size of the spleen. "CD55 KO mice also exhibited splenomegaly compared to the WT group at 10 dpi." (PMID 36036625, 2022).
squamous cell carcinoma (1 paper, 2017). A carcinoma arising from squamous epithelial cells. "However, we didn't find CD55 rs2564978 polymorphism effect on the risk of squamous-cell carcinoma (CC versus TT, OR = 0.06, 95% CI = 0.99–2.30) and other types (CC versus TT, OR = 2.36, 95% CI = 0.70–7.95)." (PMID 28008159, 2017).
steatosis (1 paper, 2022). Increased lipid within the cytoplasm of cells. "The expression of CD55 by KCs is almost undetectable in patients with severe steatosis when compared to healthy controls." (PMID 36304458, 2022).
teratoma (1 paper, 2024). A non-seminomatous germ cell tumor characterized by the presence of various tissues which correspond to the different germinal layers (endoderm, mesoderm, and ectoderm). "Transplantation of these cells that also expressed covalent single chain trimers of Qa1 and H2-Kb to inhibit NK cells and CD55, Crry, and CD59 to inhibit complement deposition led to persistent teratomas in wild-type mice." (PMID 38215755, 2024).
thymoma (1 paper, 2024). A neoplasm arising from the epithelial cells of the thymus. "CD55 and CR1 were considerably downregulated in thymoma patients." (PMID 39434140, 2024).
thyroid cancer (1 paper, 2025). "CD55 protects thyroid cancer cells from complement-mediated attack and promotes carcinogenesis by allowing tumor cells to escape from cytolysis." (PMID 40535127, 2025).
tuberculosis (1 paper, 2023). A chronic, recurrent infection caused by the bacterium Mycobacterium tuberculosis. "However, little is known about the value of complement regulatory protein (CD46, CD55, and CD59) in the differential diagnosis of tuberculosis." (PMID 36820087, 2023).
urinary bladder cancer (1 paper, 2017). A primary or metastatic malignant neoplasm involving the bladder. "To further verify that the DraE-ΔSS protein cannot form Dr fimbriae on bacterial surface, we analyzed the adhesion of fluorescent E. coli strains to urinary bladder cancer cells, to which Dr fimbriae specifically bind via the surface located CD55, CD66a, CD66c, and CD66e human protein receptors." (PMID 28739804, 2017).
uterine cancer (1 paper, 2025). Primary or metastatic malignant neoplasm involving the uterine corpus and/or the cervix. "Similarly, increased CD55 and CD59 expression was observed on cell membranes and in the TME of ovarian and uterine cancers." (PMID 40370471, 2025).
tumor (136 papers, 1992 to 2026). "It enhanced tumor growth and liver metastasis in nude mice with the concomitant increase in metastasis-associated CD55 and CD61 expression." (PMID 33758996, 2022). "One arm often targets a tumor-associated antigen while the other targets an immune system-evading surface protein (such as CD47 or CD55/59), increasing susceptibility of the tumor cell to lysis by complement or NK cells, or phagocytosis by macrophages." (PMID 34069573, 2021). "In conclusion, the human IgM antibody PAT-SC1 induces highly specific apoptosis in tumour cells expressing the tumour-specific variant of CD55." (PMID 24452482, 2014). "In addition, increased expression of CD55, another complement regulatory protein on the tumor cell surface was associated with potentially reduced survival, as suggested by prior studies." (PMID 39747856, 2025). "Silencing these CRPs induces apoptosis in vitro and inhibits tumor growth in vivo, while anti-CD55 antibodies restore complement activation and suppress CRC proliferation and invasion." (PMID 41031883, 2025). "Subsequently, we constructed a mouse axillary tumor model and used a lentivirus carrying CD55 for intratumoral injection." (PMID 40596619, 2025). "Studies have demonstrated that ADGRE5 and its ligand CD55 are co-expressed in cells of several tumor types." (PMID 40862763, 2025). "Tumor cells often overexpress membrane complement regulatory proteins (mCRPs) such as CD55, CD46, and CD59, which inhibit complement activation and protect against complement-mediated cytotoxicity." (PMID 40806542, 2025). "GB262 is a novel PD-L1/CD55 bispecific antibody that has been shown to suppress PANC-1 tumor growth in mice by increasing T cell activation, as well as antibody-dependent cell-mediated cytotoxicity (ADCC) and complement dependent cytotoxicity (CDC)." (PMID 38612911, 2024). "This cluster highly expressed CD55, a glycoprotein that can protect cells from complement-mediated attack, suggesting the clusters potential link with tumour immunity." (PMID 38906852, 2024). "These included CDA and CD55, which were upregulated in the tumor cluster and F10 upregulated in the stroma cluster." (PMID 38291365, 2024). "Metastatic cells exhibited elevated expression of SNRNP70, which was prevalent across metastatic clusters except for tumor-infiltrating lymphocytes (TILs), whereas CD55 showed low expression in all cells." (PMID 39704173, 2024). "Mechanistically, SNRNP70 directly interacted with CD55, modulating its alternative splicing and promoting tumor progression in OS." (PMID 39704173, 2024). "ST3GAL1 gene can promote immune escape of tumor cells by targeting CD55 gene, and can promote tumor angiogenesis and disease progression." (PMID 39711442, 2024). "Rituximab-sensitive cell lines (Ramos and WSU-NHL) showed CDC of 47% and 38%, respectively, and 4-1H (anti-CD55 antibody) showed CDC-induced tumor cell clearance of 10% and 21%, respectively." (PMID 37880350, 2023). "The radioisotope-labeled anti-CD55 antibody conjugated with 177Lu demonstrated its potential as a therapeutic agent by significantly reducing tumor growth and increasing the median survival time in a pleural metastatic lung cancer mouse model." (PMID 37880350, 2023). "Overexpression of CD55 in the tumor microenvironment protects cancer cells from complement-mediated attack." (PMID 36918558, 2023). "Next, we focused on CD55, a membrane-bound complement regulatory protein, in tumor cells that inhibits CDC." (PMID 37880350, 2023). "Tsao showed that survival in HER2+ breast cancer is inversely related to tumor levels of CD55 and CD59." (PMID 36291900, 2022). "To determine the effects of CD55 on tumor growth, we used shRNA to knockdown expression, which resulted in a greater than 80% decrease in expression." (PMID 36686777, 2022). "A broad range of cancer types overexpress CD55, and its involvement in tumour development and progression has been suggested." (PMID 35851954, 2022).
tumor (continued). "We also demonstrate that tumor C1q expression is positively associated with survival outcome in HER2+ BC patients and that complement regulators CD55 and CD59 were inversely correlated with outcome, suggesting the clinical importance of complement activity." (PMID 35167491, 2022). "Moving forward it will be paramount to confirm MAC development in both our fH and CD55 knockdown cells to verify the mechanism through which tumor growth is inhibited." (PMID 36686777, 2022). "CD55 is overexpressed in many of the in situ tumor cells and is further enhanced in the presence of HPV E6 protein and is responsible for radio resistance and cancer aggressiveness." (PMID 33758996, 2022). "The augmented expression of CD55 and CD59 suggested a predominant role in progression of ccRCC, whereas the amount of CD46 was significantly associated to tumour stage." (PMID 34572075, 2021). "Hypoxic tumor cells have upregulated expression of C3-C3a-C3aR axis and downregulated CD55, CD46, and FH, which play important roles in tumor cell proliferation and CSCs stemness maintenance." (PMID 33869223, 2021). "In patients with tumours overexpressing CD55, the accompanying reduction in complement activation correlated with chemoresistance and poorer outcomes." (PMID 33802004, 2021). "One study using a single cell line, A431, showed that oestrogen receptors ERα and G‐coupled protein receptor (GPR30, or GPER1) modulated expression of tumour markers Cyclin D1 and CD55; however, ERβ downregulated both tumour markers." (PMID 35664979, 2021). "In this context, it is evident that CD55 has a significant function in tumor progression, based on past studies and our findings." (PMID 32842508, 2020). "Further, we confirmed that CD55-Smad4 has a potent anti-tumor efficacy in CRC in vitro and a mouse xenograft model." (PMID 33322272, 2020). "A mouse xenograft study has shown that a blocking CD55-antibody inhibits tumor growth and increases survival of mice." (PMID 33362763, 2020). "Specifically, CD55 expression has significant correlation with tumor purity in COAD, and the expression of the complement component C3, complement receptor CR4, and complement activation regulator C5aR1 was statistically related with immune purity in STAD." (PMID 33614473, 2020). "The obtained results indicate that CD55-Smad4 suppresses cell proliferation, metastasis, and tumor stemness in CRC by regulating the Wnt/β-catenin signaling pathway." (PMID 33322272, 2020). "Previously, our study has showed that CD55‐TMn has a strong antitumour effect in mouse tumour xenograft." (PMID 33251723, 2020). "The results showed that CD55-Smad4 significantly activated caspase signaling and increased the cleavage of procaspase 3 and PARP, indicating that CD55-Smad4 can effectively induce cell apoptosis, enhancing the anti-tumor effect of CD55." (PMID 33322272, 2020). "CD55 expression was observed predominantly in the apical border of the tumor epithelial cells, showing increased distribution and intensity, in accordance with the histological grades of IPMN, whereas strong membranous staining was observed in invasive IPMN." (PMID 32842508, 2020). "The potential interaction of CD97 with CD55 situated in the extracellular matrix and its importance for tumor invasion are supported by results regarding enhanced CD97 in scattered tumor cells present in the invasion front." (PMID 32781778, 2020). "Hematoxylin and eosin (HE) staining indicated that CD55-Smad4 induced more severe cytopathic effects on tumor tissue than CD55-EGFP or PBS." (PMID 33322272, 2020). "In many cases, for example in colon cancer, CD55 serves as a marker of tumor aggression and decreased 7-year survival." (PMID 31164885, 2019). "Taken together, here we demonstrate for the first time that all three ERs- ERα, ERβ and GPR30 are expressed in human A431 cSCC cells and further ER agonist based activation modulates the expression of tumor markers CD55 and Cyclin D1." (PMID 31611744, 2019).
tumor (continued). "High expression of the mCRPs membrane cofactor protein (CD46), decay-accelerating factor (CD55), and CD59 (protectin) on tumor cells is associated with increased metastatic potential, and poor prognosis in a range of tumors." (PMID 31001273, 2019). "The present study was conducted in human cSCC cell line to confirm the expression of all three ERs and to further investigate their activation by ER agonists on modulation of tumor markers Cyclin D1 and CD55." (PMID 31611744, 2019). "In summary, this study demonstrates that tumor markers Cyclin D1 and CD55 in A431 cells can be differentially modulated via activation of three ER subtypes, suggesting the involvement of ER signals in cancer cell progression." (PMID 31611744, 2019). "As observed for tumor cells, exosomes display CD55 and CD59, conferring resistance against complement-mediated lysis, and potentially regulating the exosome-mediated cross-talk associated with the metastatic program." (PMID 31001273, 2019). "ER subtype agonist based activation on A431 cells was performed to investigate their role in modulating mRNA and protein expression of tumor markers CD55 and Cyclin D1." (PMID 31611744, 2019). "The focus of current study was to determine ER subtype specific expression on cSCC A431 cells and investigate if ER agonist based activation modulates tumor markers CD55 and Cyclin D1 in the cells." (PMID 31611744, 2019). "When analysed across the Badea microarray gene expression set, CD55 was found to have a 4.065-fold increase in the PDAC tumours (n = 39) compared to normal pancreas." (PMID 30404163, 2018). "Mechanisms of primary and/or acquired resistance include tumor-related factors, such as reduced cell surface expression levels of the target antigen and high levels of complement inhibitors (CD55 and CD59)." (PMID 30294326, 2018). "We evaluated the biodistribution (tumor uptake and intratumoral distribution) of the 177Lu-anti-CD55 antibody in vivo." (PMID 29895866, 2018). "The levels of 177Lu-anti-CD55 in tumor tissues were 1.9–4.5 times higher than those in blood and 19.7–199 times higher than those in muscle." (PMID 29895866, 2018). "CD55 is expressed in all 5 of the primary PDAC tumours, and in 4/5 of the PDX F1 and F2 tumour tissues." (PMID 30404163, 2018). "Complement decay-accelerating factor (CD55) was identified as significantly differentially expressed between primary PDAC tumours and matched adjacent-normal tissues, with a 6.77-fold increase in expression in PDAC tissue." (PMID 30404163, 2018). "High CD55 expression was observed in metastatic tumor cells (80%, 4/5) compared to NSCLC cells (53.85%, 14/26) among CD55-positive cases." (PMID 29895866, 2018). "Patients with high tumor CD55 expression at diagnosis had significantly worse progression-free survival compared with patients with low CD55 levels (hazard ratio 4.7, confidence interval 1.5–14.6, P = 0.003)." (PMID 28838952, 2017). "CD55 has been revealed to have an important role in tumor genesis, and presence of small populations of cells with strong CD55 expression would be sufficient to predict poor prognosis of several tumors." (PMID 27043658, 2016). "We have described that the small CD55+ cell subpopulation within a heterogeneous NB cell line shows aggressive tumor features with respect to CD55− cell subpopulation." (PMID 27043658, 2016). "In contrast, the CD55− cell population represents an in vitro model of tumor cells with decreased invasion, increased adhesion and reduced ability to grow and form colonies in anchorage-independent conditions." (PMID 27043658, 2016). "The present study identified a significant correlation between the intensity of CD97 and CD55 expression and tumor aggressiveness and prognosis." (PMID 25624904, 2015). "A number of studies have demonstrated that CD97 and CD55 are involved in tumor dedifferentiation, migration, invasiveness and metastasis." (PMID 25624904, 2015).